FOXO3 (forkhead box O3)
Diseases named in the same sentence as FOXO3 in open-access papers (continued):
Sharing a sentence is not in itself a finding about the gene and the disease.
neuronal tumor (4 papers, 2013 to 2020). Neuronal brain tumors are an uncommon group of central nervous system tumors that arise from cells with neuronal differentiation. "In neuronal tumor cells the protein-kinase-B (PKB) is frequently hyper-activated causing phosphorylation and functional inactivation of FOXO3." (PMID 31591479, 2020). "One explanation for this effect of FOXO3 inhibition in the 3D culture model is, that FOXO3 activity is elevated in spheroids derived from neuronal tumor cells per se, which initiates drug resistance, possibly through FOXO3-triggered activation of autophagy." (PMID 31591479, 2020). "Together, these findings demonstrate that FOXO3 induces the expression of LUM, and that RPG efficiently represses FOXO3-mediated LUM induction in neuronal tumor cells." (PMID 31861249, 2019). "Collectively, our data indicate that RPG is capable of silencing the transcriptional activity of FOXO3 in neuronal tumor cells." (PMID 31861249, 2019). "In summary, these results indicate that FOXO3-mediated migration depends on LUM expression in neuronal tumor cells." (PMID 31861249, 2019). "In line, the repression of p62 by FOXO3 was abolished by CQ, which supports the notion that FOXO3 induces autophagic flux in neuronal tumor cells." (PMID 28545464, 2017). "In neuronal tumor cells DNA-damaging chemotherapeutic agents activate the transcription factor FOXO3 which regulates the formation of reactive oxygen species (ROS) and cell death as well as a longevity program associated with therapy resistance." (PMID 28545464, 2017). "In neuronal tumor cells, FOXO3 triggers ROS-accumulation as a consequence of transient mitochondrial outer membrane permeabilization, which is essential for FOXO3-induced apoptosis in these cells." (PMID 23801966, 2013). "However, as exclusively FOXO3 is expressed in the analyzed high-stage NB cell lines, this study was designed to investigate the efficacy of CBX to inhibit FOXO3 in order to overcome chemoprotection in neuronal tumor cells." (PMID 31591479, 2020). "In summary, these results show that the transcription factor FOXO3 binds to the MMP-9 and MMP-13 promoters and elevates the MMP-13 enzymatic activity in neuronal tumor cells." (PMID 31861249, 2019). "RPG interferes with the FOXO3-DBD and thereby silences the transcriptional activity of FOXO3 in neuronal tumor cells." (PMID 31861249, 2019). "Hence, we investigated the impact of FOXO3 on MMP-9 and MMP-13 promoter activity in the aggressive neuronal tumor cell lines IMR32 and SK-N-SH." (PMID 31861249, 2019).
pulmonary arterial hypertension (4 papers, 2022 to 2024). Pulmonary arterial hypertension (PAH) is a group of diseases characterized by mean pulmonary artery pressure >20 mmHg and elevated pulmonary arterial resistance leading to right heart failure. "miR-629-5p has been shown to be upregulated in the plasma of patients with pulmonary arterial hypertension and also in hypoxic pulmonary artery smooth muscle cells, promoting vascular remodeling via FOXO3 and PERP." (PMID 39201485, 2024).
tuberculosis (4 papers, 2019 to 2025). A chronic, recurrent infection caused by the bacterium Mycobacterium tuberculosis. "It has been shown that miR-223 is upregulated in patients with active tuberculosis and that it suppresses macrophage apoptosis in tuberculosis via FOXO3, which is crucial for the immune response to M. tuberculosis." (PMID 40141021, 2025). "For example, FOXO3 overexpression is shown to counteract the miR-223 inhibitory effect on apoptosis in active tuberculosis patients." (PMID 33520966, 2020). "The dual functions of FOXO3 as an inducer of macrophage apoptosis and inhibitor of IL-10 secretion, suggest that this factor can be proposed as a new target for host-directed therapy against Tuberculosis." (PMID 31921181, 2019).
acute leukemia (3 papers, 2014 to 2020). A clonal (malignant) hematopoietic disorder with an acute onset, affecting the bone marrow and the peripheral blood. "They reported that MLL-FOXO4 (a chimeric protein product of a genomic translocation that arises in a small number of acute leukemia cases) was able to suppress FOXO3-mediated apoptosis in Ba/F3 cells as well as FOXO3 -mediated transcriptional activation." (PMID 25806826, 2015).
Anxiety (3 papers, 2021 to 2024). Intense feelings of nervousness, tension, or panic often arise in response to interpersonal stresses. "Brain-specific deletion of Foxo1 driven by the Nestin promoter results in increased anxiety in a forced swim test, contrary to the reduced anxiety in Foxo3-deficient mice." (PMID 34727995, 2021). "After phenotype scanning, FOXO3 (rs3813498) was linked to intelligence and height, while ITIH3 (rs2071044) was associated with anxiety/tension." (PMID 39221148, 2024). "Moreover, some significant genes within these nominally significant overlapping pathways have been previously associated with pain problems and/or anxiety symptoms (e.g., the ZNRD1 gene; the MDK gene; the FOXO3 gene; the COMT gene; the NFATC4 gene)." (PMID 37146008, 2023).
benign prostate hyperplasia (3 papers, 2019 to 2023). "At the top of the list of proteins modified by FOXO3 genotype is neural epidermal growth factor-like like 2 (NELL2) that causes cell proliferation and inhibition of apoptosis when overexpressed in benign prostate hyperplasia." (PMID 36881352, 2023).
bladder tumors (3 papers, 2014 to 2018). "Up- and downstream FOXM1 regulators (e.g., FOXO3, PI3k, AKT) may be valuable drug targets and should be further explored also in bladder tumors." (PMID 29959570, 2018).
brain tumor (3 papers, 2016 to 2018). "Interestingly, in contrast with the other tumors, slight significant overexpression of FOXO1 was observed in brain tumours, and the expression of FOXO3 was found to be overexpressed in some of these tumors." (PMID 29484124, 2018).
Cirrhosis (3 papers, 2021 to 2024). A chronic disorder of the liver in which liver tissue becomes scarred and is partially replaced by regenerative nodules and fibrotic tissue resulting in loss of liver function. "Upregulation of inflammatory factors such as IL-6 in cirrhosis enhances the activation of the IL-6/AMPK/FoxO3 axis." (PMID 37881635, 2023). "All cirrhosis patients had lower EIF2 signaling levels and higher expressions of the transcription factor FOXO3 compared to controls." (PMID 38369527, 2024). "In regard to clinicopathological factors evaluated other than invasion, there was not a significant association between FOXO3 overexpression and AFP levels, cirrhosis, gender, HBV infection, metastasis, TNM staging, tumor nodularity or tumor size." (PMID 34771514, 2021).
cutaneous melanoma (3 papers, 2012 to 2024). A primary melanoma arising from atypical melanocytes in the skin. "Recently, studies of aberrant miR-182 expression demonstrated that miR-182 promotes cutaneous melanoma metastasis by suppressing the transcription factors FOXO3 and MITF." (PMID 22848417, 2012). "Many of them were previously appreciated in the genome of skin melanomas (e.g., MITF, NOTCH2, PD-L1 and JAK2 amplifications, or CDKN2A deletions); however, the CNAs in genomic locations harboring PAX5, ETS1, BCL7, RAD51, APAF1, FOXO3 and CTNNA1 are novel." (PMID 33779796, 2021).
dilated cardiomyopathy (3 papers, 2021 to 2024). Cardiomyopathy which is characterized by dilation and contractile dysfunction of the left and right ventricles. "We identified up-regulation of gene FOXO3 (Forkhead Box O3, 602681) in cardiac fibroblasts, which can further help us identify dilated cardiomyopathy." (PMID 39202774, 2024). "For example, FOXO3-null mice developed dilated cardiomyopathy within 12 weeks of age." (PMID 35004893, 2021).
gastric tumor (3 papers, 2013 to 2021). "Immunocytochemistry confirmed that the expression of FOXO3 was distributed to the cytoplasm of organoid cells, indicating that Gan mice develop FOXO3-Cyt-type gastric tumors." (PMID 33795838, 2021). "To further examine the tumor-suppressor role of FOXO3, we established organoids from gastric tumors of Tam-untreated Gan Foxo3+/+, Gan Foxo3+/Act, and Gan Foxo3Act/Act mice." (PMID 33795838, 2021). "In Gan mouse gastric tumors, the expression of FOXO3 was detected by immunoblotting, and the expression was significantly higher than that of wild-type mouse stomach." (PMID 33795838, 2021). "To further examine the role of FOXO3, we established organoids from Gan mouse gastric tumors." (PMID 33795838, 2021). "Importantly, gastric tumor development was suppressed in Gan Foxo3+/Act mice, and the mean tumor area measured on the histology sections decreased significantly to 24.0% of that in control Gan Foxo3+/+ mice." (PMID 33795838, 2021).
hearing loss (3 papers, 2017 to 2023). "As this is a cohort study, suprathreshold audiometry is necessary in the follow-up examination of these noise exposed workers to detect "hidden hearing loss" and verify the role of FOXO3 gene variation in noise induced hearing loss." (PMID 29220389, 2017). "It has been shown that mice are susceptible to adult-onset hearing loss with the hallmark characteristics of auditory neuropathy, namely, elevated auditory thresholds combined with normal outer hair cell function if lacking the transcription factor Foxo3." (PMID 29220389, 2017).
HIV-1 infection (3 papers, 2014 to 2017). The type species of lentivirus and the etiologic agent of acquired immunodeficiency syndrome (AIDS). "In parallel, oral epithelial cells exhibited increased expression of regulatory factors such as Trex and Foxo3, suggesting an active role in regulating persistent inflammation and the immune activation role of IFNs, which may contribute to a low risk of HIV-1 infection in oral mucosal cells." (PMID 27168019, 2016).
latent infection (3 papers, 2018 to 2024). "In this study, we found that KSHV latent infection of B lymphoma cells significantly enhance the antioxidant capacity by upregulating both forkhead box protein O1 (FoxO1) and FoxO3." (PMID 37594999, 2023). "We found that KSHV latent infection slightly while robustly upregulates FoxO1 and FoxO3, respectively, which is essential for KSHV-positive B lymphoma cells to defend oxidative stress." (PMID 37594999, 2023). "We have recently reported that KSHV latent infection significantly upregulate FoxO1 and FoxO3 to ablate oxidative stress in KSHV-transformed cells." (PMID 37594999, 2023). "Consistently, KSHV latent infection slightly upregulated FoxO1 while dramatically upregulated FoxO3 in BJAB cells." (PMID 37594999, 2023). "Moreover, the protein expression of both FoxO1 and FoxO3 was robustly increased following KSHV latent infection of rat primary metanephric mesenchymal precursor (MM) cells." (PMID 37594999, 2023). "Here we identified FoxO1 and FoxO3 as the key antioxidant genes and KSHV latent infection upregulated both of them, which helps PEL cells to resist oxidative stress." (PMID 37594999, 2023). "Mechanistically, we identified forkhead box protein O1 (FoxO1) and FoxO3 as irrevocable antioxidant defense genes and both of them are upregulated by KSHV latent infection, which is essential for the promoted ROS scavenging in KSHV-positive B lymphoma cells." (PMID 37594999, 2023).
metabolic dysfunction-associated steatotic liver disease (3 papers, 2017 to 2025). Metabolic dysfunction-associated steatotic liver disease (MASLD, formerly known as nonalcoholic fatty liver disease or NAFLD) is a type of liver disease that is not caused by alcohol. "MiR-421 has been shown to act upstream of FOXO3 in the regulation of lipid metabolism in a nonalcoholic fatty liver disease mouse model." (PMID 28870167, 2017). "FOXO3 restores autophagy flux and attenuates the activation of the NLRP3 inflammasome in Kupffer cells by promoting the transcription of Bim (BCL2L11), suggesting that this could be a potential therapeutic target in non-alcoholic fatty liver disease and other obesity-related diseases." (PMID 36881352, 2023).
metastatic tumors (3 papers, 2013 to 2022).
myelodysplastic syndrome (3 papers, 2017 to 2024). A clonal hematopoietic disorder characterized by dysplasia and ineffective hematopoiesis in one or more of the hematopoietic cell lines. "FOXO3 hypermethylation is fundamental in the pathophysiology of several cancers, and it has been related to the progression of myelodysplastic syndromes." (PMID 39525284, 2024).
pheochromocytoma (3 papers, 2012 to 2025). "The cluster analysis showed that SDH-deficient GISTs and SDHB-mutant pheochromocytoma/paraganglioma shared the expression of hypoxia genes that is particularly evident for FOXO3, VLDLR, and ENO2." (PMID 33806389, 2021).
pituitary adenoma (3 papers, 2018 to 2024). "One exception was female Foxo3−/− mice, in which occurrence of pituitary adenoma was accelerated compared with WT and Foxo3+/− mice." (PMID 31888201, 2019). "Matrine, an alkaloid derived from the roots of Sophora flavescens, inhibits the proliferation of pituitary adenoma cells by promoting the nuclear localization of forkhead box O3A (Foxo3a) through the inhibition of the Protein Kinase B (Akt)/Foxo3a signaling pathway." (PMID 39765842, 2024).
prediabetes (3 papers, 2016 to 2026). "miR-27 was up-regulated in obese prediabetes, targeting regulators of oxidative stress and apoptosis such as BCL2, BMI1, FOXO3, and suppressing SIRT1, thereby amplifying IL-6 production." (PMID 41400625, 2025).
preeclampsia (3 papers, 2020 to 2025). Preeclampsia is a hypertensive disorder of pregnancy that is characterized by new-onset hypertension with proteinuria presenting after 20 weeks of gestation, and depending on mild or severe forms may initially present with severe headache, visual disturbances, and hyperreflexia. "In the study, we devote to investigate the associations of FOXO3 and TLR7 genetic polymorphisms with preeclampsia in a Chinese population." (PMID 33317466, 2020).
schizophrenia (3 papers, 2016 to 2023). A major psychotic disorder characterized by abnormalities in the perception or expression of reality. "The cerebral cortex underlies the higher-order cognition of humans, and GWASs indicate that intronic variants of FOXO3 are correlated with the surface area of the human cerebral cortex, cortical thickness, brain volume, vertex-wise sulcal depth, intelligence, and schizophrenia." (PMID 37789379, 2023). "Here, we show that bepridil (BPD) and trifluoperazine (TFP), which are FDA-approved drugs for treatment of schizophrenia and angina respectively, inhibit Akt-pS473 phosphorylation and promote FOXO3 nuclear localization and activation in TNBC cells." (PMID 27283899, 2016).
serous ovarian cancer (3 papers, 2014 to 2019). "Loss of FOXO3 has been reported to be an early event in the development of high-grade serous ovarian cancer, and low levels of FOXO3 are associated with poor patient survival." (PMID 31013711, 2019). "FOXO3 downregulation has also recently been reported in high-grade serous ovarian carcinoma." (PMID 24887297, 2014).
temporal lobe epilepsy (3 papers, 2017 to 2023). A localization-related (focal) form of epilepsy characterized by recurrent seizures that arise from foci within the temporal lobe, most commonly from its mesial aspect. "Augmentation of FOXO3 is associated with epileptic severity and temporal lobe epilepsy." (PMID 37880579, 2023). "Expression of neuronal mitochondrial FOXO3 was increased in patients with temporal lobe epilepsy as compared to the controls." (PMID 37880579, 2023). "In patients with temporal lobe epilepsy, high level of FOXO3a was found in the mitochondrial fraction of hippocampus, which indicates that FOXO3 may act as a target that affects neuronal apoptosis via modulation of ROS generation in brain pathologies including epilepsy." (PMID 31191222, 2019).
urinary bladder urothelial carcinoma (3 papers, 2020 to 2025). "Additionally, recent reports have indicated that BCL6 suppresses FOXO3 activity through the activation of the PI3K‒AKT signaling pathway in urinary bladder urothelial carcinoma." (PMID 40777995, 2025).
abdominal aortic aneurysm (2 papers, 2021). Enlargement and ballooning of the vessel that supplies arterial blood to the abdomen, pelvis and legs. "In addition, we also found that FoxO1 was upregulated in abdominal aortic aneurysm tissues, however, this study only focused on FoxO3, the role of FoxO1 in AAA needs to be further explored in the future." (PMID 33828087, 2021).
alcoholic hepatitis (2 papers, 2014 to 2018). Acute hepatitis resulting from ingestion of alcohol. "Monocytes from patients with alcoholic hepatitis fail to undergo normal FOXO3 phosphorylation and apoptosis in response to LPS37." (PMID 29531813, 2018). "Further evidence supporting a role of FOXO3-dependent myeloid cell apoptosis in adaptation of the liver to alcohol comes from recent studies from our lab showing that alterations of myeloid cell FOXO3 function are present in alcoholic hepatitis patients." (PMID 29531813, 2018).
alcoholic liver damage (2 papers, 2017 to 2019). "FoxO3 can increase Bcl-2 expression under normal conditions and in alcoholic liver disease, while acetylated-FoxO3 has been shown to have lost this protective function." (PMID 28250026, 2017). "Moreover, research haa shown that various pathways, such as AMPK-Forkhead box O3 (FOXO3A) axis, sorting nexin 10 (SNX10)/chaperone, ALDH2, cannabinoid receptor 2 can induce autophagy to prevent alcoholic liver damage." (PMID 31159489, 2019).
androgenic excess (2 papers, 2013 to 2021). "A brief overview of the in-silico computational strategy demonstrated that FoxO3 is a promising target of miR-21-5p, which might be projected as an intricate network in PCOS, contributing through androgenic excess." (PMID 33992122, 2021).
anemia (2 papers, 2013 to 2025). A reduction in the number of red blood cells, the amount of hemoglobin, and/or the volume of packed red blood cells. "For example, deletion of transcription factor forkhead box o3 (Foxo3) only mildly affects erythroid cell function, but strongly exacerbates anemia and hemolysis to the point of lethality upon oxidative stress." (PMID 24367609, 2013).
ankylosing spondylitis (2 papers, 2022 to 2025). An autoimmune chronic inflammatory disorder characterized by inflammation in the vertebral joints of the spine and sacroiliac joints. "This study aimed to investigate whether Forkhead box O3a (FOXO3a) modulates inflammation and oxidative stress in ankylosing spondylitis (AS)." (PMID 35784335, 2022).
aortic aneurysm (2 papers, 2021 to 2022). A ruptured aneurysm located in the wall of the proximal portion of the descending aorta proceeding from the arch of the aorta. "Among them, FOXO3 was reported to promote VSMC phenotypic switching to accelerate aortic aneurysm formation." (PMID 35359572, 2022).
autoimmune thyroid disease (2 papers, 2018 to 2025). Inflammatory disease of the thyroid gland due to autoimmune responses leading to lymphocytic infiltration of the gland. "Although FOXO-3 is more widely studied in the context of longevity and metabolic regulation rather than thyroid autoimmunity, its role in stress response and immune modulation (e.g., via chromatin hubs and enhancer regulation) has been described." (PMID 41470831, 2025).
chondrosarcoma (2 papers, 2021 to 2022). A malignant cartilaginous matrix-producing mesenchymal neoplasm arising from the bone and soft tissue. "Specifically, overexpression of miR-34a enables chondrosarcoma cells to overcome resistance to carbon-ion irradiation by upregulating FOXO3, which leads to KLF4 repression." (PMID 36326232, 2022). "The effect of miR-34 and miR-142–3 p in radioresistance in chondrosarcoma and ATRT have been identified by regulating the transcription factors FOXO3 and SOX2, respectively." (PMID 36326232, 2022).